Y_RNA (Y RNA )
Gene: Miscellaneous RNA gene on chromosome 11 (8,943,380 to 8,943,467, reverse strand). Ensembl gene ENSG00000223080.
Homologues: Orthologues: chimpanzee Y_RNA (91% identical), dog Y_RNA (52% identical), mouse Gm24629 (52% identical), guinea pig Y_RNA (49% identical), macaque Y_RNA (45% identical), pig Y_RNA (42% identical), macaque Y_RNA (40% identical), guinea pig Y_RNA (39% identical), macaque Y_RNA (39% identical), macaque Y_RNA (38% identical), rabbit Y_RNA (38% identical), tropical clawed frog Y_RNA (38% identical), and 3 more. Paralogues in human: Y_RNA (70% identical), RNY4P25 (67% identical), RNY4P6 (67% identical), Y_RNA (67% identical), RNY4 (66% identical), RNY4P14 (66% identical), RNY4P29 (66% identical), Y_RNA (66% identical), RNY4P36 (65% identical), RNY4P7 (65% identical), RNY4P9 (65% identical), Y_RNA (65% identical), and 80 more.